KRAS (KRas proto-oncogene, GTPase)
Diseases named in the same sentence as KRAS in open-access papers (continued):
Sharing a sentence is not in itself a finding about the gene and the disease.
colorectal cancer (continued). "However, members of the miR181 family have been reported as tumor suppressors in other cancers such as AML, colorectal cancer, and lung cancer, and KRAS was recently proposed as a direct target of miR181a in AML." (PMID 31874105, 2020). "Oncogenic mutation within the KRAS gene represents a negative predictor for treatment response to anti-epidermal growth factor receptor (EGFR) in patients with colorectal cancer." (PMID 33002027, 2020). "Colorectal cancer cells harboring KRAS or BRAF mutation show a higher expression of RREB1 compared with tissue samples without KRAS or BRAF mutation." (PMID 32210733, 2020). "In various tumor-bearing mouse model, such as KRAS-mutant colorectal cancer, BRAFV600E-mutant melanoma, and triple-negative breast cancer, the inhibition of MEK demonstrated better efficacy in combining with antibodies targeting PD-1 or PD-L1, compared to single agent." (PMID 32508809, 2020). "In colorectal cancer (CRC), KRAS mutational status is critical for targeted therapy because it can predict the therapeutic response to anti-epidermal growth factor receptor (EGFR) treatment; consequently, KRAS genotyping is routine in patients with metastatic CRC." (PMID 33585224, 2020). "Colorectal cancer (CRC) is associated with resistance to anti-epidermal growth factor receptor (EGFR) antibodies (both acquired and intrinsic), owing to the amplification or mutation of the KRAS oncogene." (PMID 32703218, 2020). "In a case-control study conducted in Spain, researchers found that a higher serum concentration of organochlorine compounds was associated with an elevated risk of colorectal cancer with KRAS− but not with KRAS+." (PMID 32723394, 2020). "KRAS status in the tumor tissue of primary colorectal cancer (CRC) was available in 63 pts." (PMID 32867151, 2020). "Decreased levels of the media component l-alanyl-l-glutamine (stable and non-toxic glutamine source) were found for colorectal cancer cells harbouring G13D, G12A, G12D, G12V and G12R mutations compared to their background-matched KRAS wild type cancer cells." (PMID 32300895, 2020). "For example, lung and colorectal cancers with mutations in KRAS or BRAF do not respond to treatment with anti-EGFR therapies." (PMID 32087721, 2020). "The use of VPE in functional foods or nutraceuticals could be exploited in personalized anti colorectal cancer dietary strategies, because higher sensitization to the drug 5-FU is achieved in BRAF mutated tumors, relative to KRAS mutated tumors." (PMID 32806531, 2020). "This was expanded on by characterizing metabolic phenotypes of KRAS-mutant colorectal carcinomas." (PMID 32765953, 2020). "Moreover, the YAP1/six2 axis is required for DDX3-mediated tumor aggressiveness and cetuximab resistance in KRAS wild-type colorectal cancer." (PMID 30832689, 2019). "To explore the underlying mechanism mediating this effect we initially investigated cell growth in COLO320DM (APC mutated/KRAS WT) and HCT-15 (APC mutated/KRAS mutated) colorectal cancer cells under the influence of 1 μM G007-LK (TNKS inhibitor; TNKSi) and/or 1 μM GDC-0973 (MEK inhibitor; MEKi)." (PMID 30717152, 2019). "Similarly, oncogenic KRAS, which is a well-known oncogene necessary for cancer initiation and maintenance of tumor growth, can also drive invasion and maintain metastasis in colorectal cancer." (PMID 31589613, 2019). "Notably, KRAS wt colorectal cancers exhibited a significantly higher proportion of CD8+ CTLs among T cells but also higher Treg measures (absolute count and the proportion of Tregs among CD4+ cells." (PMID 31307428, 2019). "For example, pre-clinical studies demonstrated that combined rapamycin and L-asparaginase, which depletes cells of both glutamine and asparagine, can synergistically inhibit the growth of KRAS-mutant colorectal cancer cells that have upregulated asparagine synthetase." (PMID 31817676, 2019).
colorectal cancer (continued). "In addition, DDX3X-dependent aggressiveness and drug resistance to cetuximab treatment have been revealed to be modulated by the YAP1-SIX2 signaling axis in KRAS wild-type colorectal cancer in both cell and animal models." (PMID 31906196, 2019). "Although we conducted four human colorectal cancer cell lines in this experiments, did not confirm other human colorectal cancer cell lines harboring KRAS, BRAF and PIK3CA mutation and patients-derived MEK inhibitor resistance colorectal cancer cells." (PMID 31769426, 2019). "Lastly, the indirect control of NEAT1/KRAS was confirmed with small interfering RNA and antisense oligonucleotides both in vitro and in vivo, providing novel insight into the lncRNA‐based oncological therapeutic approach to treat human colorectal cancer." (PMID 30575330, 2019). "It has been reported that molecular diagnosis for guiding targeted therapies, such as KRAS and BRAF mutation test in colorectal cancer, HER-2 amplification test in breast cancer, and BRAF mutation test in melanoma, become more and more important in cancer management." (PMID 31136302, 2019). "We found that there was inconsistency in the frequency distribution of CNAs in both of the data sets for those actionable genes from our list which are considered promising druggable targets for NSCLC, and colorectal cancer, such as KRAS, BRAF, EGFR, ATM, and PIK3CA." (PMID 30728399, 2019). "Here, we find graded ERK phosphorylation correlating with cell differentiation in patient-derived colorectal cancer organoids with and without KRAS mutations." (PMID 31266962, 2019). "We found that HER2 amplification is rare and poorly associated to IHC overexpression in extracolonic and extragastric GIT cancers; however in KRAS wild type colorectal cancers, which fail conventional treatment, HER2 IHC may be useful and should be considered." (PMID 31221175, 2019). "Moreover, another recent report shows that blocking KRAS-dependent ERK1/2 signaling in colorectal cancers activates JAK/STAT3 signaling." (PMID 30777101, 2019). "KRAS plays a role in promoting oncogenic events in colorectal cancer." (PMID 31552087, 2019). "BNA-clamp PCR accurately detected KRAS, NRAS and BRAF mutations in patients with colorectal cancer." (PMID 31711486, 2019). "In addition, patients with KRAS-wild type colorectal cancer are treated with the epidermal growth factor receptor (EGFR) antibody cetuximab or panituzumab in combination with chemotherapy." (PMID 31769426, 2019). "Neither APC nor KRAS mutations alone induce a colorectal cancer phenotype, although APC mutations also induce RAS activation through inactivation of glycogen synthase kinase 3β (GSK3β)." (PMID 30717152, 2019). "We focused on colorectal cancer (CRC) with distinct KRas activation levels." (PMID 30760703, 2019). "KRAS, NRAS and BRAF mutations occur in colorectal cancers in a mutually exclusive manner." (PMID 31711486, 2019). "Furthermore, the β-catenin/ZEB1 axis is activated by DDX3X-dependent KRAS transcription to promote colorectal cancer invasion." (PMID 31906196, 2019). "In addition, in a phase I study of the MEK inhibitor RO4987655, progressive disease was observed in patients with KRAS/PIK3CA-mutant colorectal cancer." (PMID 31769426, 2019).
colorectal cancer (continued). "Other genotypes are associated with a predicted lack of response to therapy e.g., mutant KRAS in colorectal cancer is associated with a lack of response to the therapeutic cetuximab." (PMID 31608239, 2019). "The uncoupling of mutational KRAS status and pathway activation is not unprecedented, as shown in pancreatic adenocarcinoma and colorectal cancer." (PMID 30925167, 2019). "Retrospective analysis of the previous blood samples revealed detectable levels of KRAS mutant ctDNA prior to immunotherapy (3 c/mL), suggesting that colorectal cancer may have already been present at the time of stage IV melanoma diagnosis." (PMID 31727009, 2019). "KRAS mutations have been reported as a reliable biomarker for epidermal growth factor receptor (EGFR) targeted therapy and are also associated with poor prognosis in colorectal cancer (CRC) patients." (PMID 30791218, 2019). "Currently, there is no positive biomarker available for selection of cancer types that are favorable to anti-EGFR mAbs, although KRAS mutations are a negative predictor for anti-EGFR mAbs in treating colorectal cancer." (PMID 31508364, 2019). "Quercetin can suppress miR-21 to alleviate TGF-β-induced fibrosis and activate the JNK pathway to induce apoptosis in KRAS-mutant colorectal cancer cells and also could inhibit the SHH pathway to regulate pancreatic cancer stem cell characteristics." (PMID 31019539, 2019). "On the other hand, 30% to 40% of patients with KRAS-mutated colorectal cancer do not benefit from Cetuximab therapy." (PMID 30577618, 2018). "However, EGFR remains a valid target in colorectal cancer within the population of patients wild-type for KRAS, NRAS, and BRAF, with proven clinical benefit." (PMID 29254887, 2018). "The various pathways of colorectal cancer development result in tumor subtypes that can be classified according to combinations of the main molecular abnormalities, including MSI, CIMP, CIN, BRAF mutations and KRAS mutations." (PMID 29652830, 2018). "The FCGR2A genotype was associated with efficacy but not with toxicity in wild‐type KRAS, cetuximab‐treated colorectal cancer patients." (PMID 30318772, 2018). "Only KRAS/NRAS mutations in colorectal cancer do not result in discriminable protein profiles comparing wild-type and mutated cases, whereas an effect can be observed for thyroid cancer and melanoma." (PMID 30442178, 2018). "However, only a few types of cancer, such as non-small cell lung cancer (NSCLC) and KRAS wild-type colorectal cancer, exhibit significant, but transient, effectiveness." (PMID 29358623, 2018). "Such screens have been used to identify cellular signalling pathways that cause resistance to immunotherapy in the context of melanoma, to identify liver tumour suppressors, to identify suppressors in glioblastoma and to study essential genes in the context of mutant KRAS colorectal cancers." (PMID 29561791, 2018). "Given the specific cytotoxic effect of C19 in KRAS-dependent LoVo cells in vitro, we next tested whether C19 exhibits antitumor activity in a colorectal cancer xenograft model using LoVo cells." (PMID 30382908, 2018). "Thus, panitumumab shows significant improvement in overall survival rate for wild type KRAS, validating as a cost effective therapeutic for colorectal cancer therapy." (PMID 29484148, 2018). "Several studies indicated that different mutation types of KRAS, NRAS, and BRAF gene in colorectal cancer tissues have different biological characteristics and lead to different biological changes, which may have different effects on patients." (PMID 30416987, 2018).
colorectal cancer (continued). "Unlike stage II/III disease, the standard of care for colorectal cancer patients with metastatic disease is driven by the presence or absence of KRAS mutations." (PMID 30118499, 2018). "The present study, therefore, provides no conclusive evidence for a role of the SNP in KRAS or BRAF-mutated colorectal cancer development." (PMID 29694444, 2018). "In this study, we systematically described and statistically analyzed the frequencies and distributions of KRAS/NRAS/BRAF genetic mutation status and their relationship with IHC in 260 cases with colorectal cancer or gastric cancer through retrospective analysis." (PMID 30416987, 2018). "We clarified the clinical prevalence of ovarian metastases from colorectal cancers (CRCs) in 296 female patients with CRC and evaluated clinical outcomes with relation to their mutational profiles, such as BRAF/KRAS mutation and microsatellite instability (MSI) status." (PMID 29662660, 2018). "The suppressive effects were investigated with the KRAS-driven colorectal cancer cell-line, SW480." (PMID 30577618, 2018). "Because RAS mutations are assessed in the routine diagnosis of colorectal carcinoma to assign epidermal growth factor receptor (EGFR) blockade therapy, we selected cells that are either wild-type for KRAS (HT-29), or carry the G12D and G13D mutations (LS174T and LoVo, respectively)." (PMID 29941002, 2018). "Furthermore, the importance of DpR in predicting PPS was reported in KRAS wild-type colorectal cancer patients treated with cetuximab-based chemotherapy, implying that this notion can be applied to other tumor types and anti-tumor agents." (PMID 28415714, 2017). "Recently, several lines of evidence suggest that colorectal cancer containing a BRAF p.V600E mutation possesses more malignant potential when compared with other genotypes of colorectal cancer, including the KRAS/BRAF-wild-type tumor and the KRAS-mutated tumor." (PMID 29115941, 2017). "Mutated BRAF and KRAS oncogenes, both members of the Mitogen Activated Protein Kinase (MAPK) pathway, are respectively observed in approximately 10–20% and 35–42% of the sporadic colorectal cancers." (PMID 28125730, 2017). "KRAS and NRAS mutated colorectal cancers (CRC) are known to be resistant to epithelial growth factor receptor (EGFR)-targeted therapy, suggesting that this type of treatment may also be ineffective in PMP." (PMID 28426742, 2017). "We further analyzed the association of EZH2 expression with the efficacy of anti-EGFR therapy in patients with colorectal cancer with no mutations in KRAS (codon 61/146), NRAS (codon 12/13/61), or BRAF (codon 600)." (PMID 28147317, 2017). "We also analysed an additional colorectal cancer cell line DLD1, which, like HCT116, has a KRASG13D mutation, and an isogenic counterpart in which the mutated KRAS allele is knocked out to leave only wild-type KRAS (DLD1 KRAS+/-)." (PMID 28806777, 2017).
colorectal cancer (continued). "Combining a MEK1/2 inhibitor with ABT‐263 is also effective in vivo, including in xenograft models of the KRAS‐mutant colorectal cancer cell lines (HCT116, SW620, SW1463) and a genetically engineered KRAS‐driven lung cancer mouse model where the combination caused 70–80% tumour regression." (PMID 28548464, 2017). "Moreover, clinical studies also have found that activating mutations in the KRAS, RAF and MEK proto-oncogenes enhance colorectal cancer resistance to GEF." (PMID 26461472, 2017). "We think that this variant likely points to a local polymorphism within the KRAS that is independent of colorectal cancer transformation." (PMID 28002797, 2017). "However, many cancers, such as colorectal cancers, contain KRAS/BRAF mutant genes and are resistant to MEKi, BRAFi, or RTKis treatments." (PMID 28002807, 2017). "To test this concept further, we utilised two cell lines with basally high mTORC1 signalling: the NCI-H460 large cell lung cancer cell line which has PI3KCA, CDKN2A, STK11 and KRAS mutations and the HCT116 colorectal cancer cell line, which contains an activating RAS mutation and PIK3CA mutation." (PMID 28415776, 2017). "Targeting RAD51, a downstream effector of homologous recombination repair (HRR) or CHK1 inhibition, thus may offer a novel strategy in killing mutant KRAS‐dependent colorectal cancers." (PMID 28173629, 2017). "As PIK3CA mutations often coexist with KRAS and BRAF mutations in advanced cancers, including colorectal cancers, combination of AKT inhibition with panRAF inhibition are expected to induce at a minimum additive effects in both KRASmut/PIK3CAmut and BRAFmut/PIK3CAmut CRC models." (PMID 27999210, 2017). "Furthermore, KRAS4A represented 15–50% of total KRAS expression in 17 human colorectal cancer samples indicating highly context-dependent regulation of KRAS splicing." (PMID 28117393, 2017). "For our purpose of validating the GECM approach, we were particularly interested in the cell viability reduction data for our top candidate compounds in colorectal cancer cell lines with and without KRAS mutation." (PMID 27965461, 2017). "The IdyllaTM KRAS Mutation Test allows for a fast and reliable analysis of FFPE samples with a turnaround-time of two hours without the need of molecular infrastructure or expertise in order to guide the personalized treatment of colorectal cancer patients." (PMID 28201998, 2017). "Negative correlations were observed between KRAS mutation and other biomarkers in the proximal colon cancer network, but not in the distal colorectal cancer network." (PMID 28623901, 2017). "Targeted therapies are currently in use to treat colorectal cancer with the monoclonal antibodies bevacizumab, cetuximab, and panitumumab; however, they are only effective in patients with tumors lacking KRAS mutations." (PMID 28906489, 2017). "In support of this hypothesis, Yun and colleagues recently showed that intracellular reduction of DHA to AA killed glycolysis-driven KRAS and BRAF mutated colorectal cancer cells through inhibition of glycolysis resulting in ATP depletion." (PMID 28737676, 2017). "Our data in combination with our prior publications on a KRAS mutated negative cell line point to NDRG2 as a potential therapeutic target for colorectal cancer." (PMID 29399558, 2017). "Similarly, the Fc-optimized anti-EGFR mAb imgatuzumab (Roche Glycart) is tested in Phase I/II clinical trials for head and neck cancer and in KRAS mutant colorectal cancer." (PMID 28620386, 2017). "Interestingly, VLX60 exhibited a trend towards specific activity against both KRAS- and BRAF mutated tumor cells from patients with colorectal cancer." (PMID 28415818, 2017).